GLA (galactosidase alpha)
Description:
Catalyzes the hydrolysis of glycosphingolipids and participates in their degradation in the lysosome.
Synonyms: GALA
Tractability: Small molecule: an approved drug acts on it; a structure with a bound ligand is known; a high-quality ligand is known; it has a high-quality binding pocket; it belongs to a druggable protein family. Antibody: its Gene Ontology location is reachable by antibodies, with high confidence; UniProt predicts a signal peptide or a membrane-spanning region. PROTAC: ubiquitination databases record sites on it; its protein half-life has been measured; a small molecule that binds it is known.
Target class: Enzyme; Hydrolase
Gene: Protein-coding gene on chromosome X (101,393,273 to 101,408,012, reverse strand). Ensembl gene ENSG00000102393.
Subcellular location: Lysosome
Pathways (Reactome):
Immune System: Neutrophil degranulation
Metabolism: Glycosphingolipid catabolism
Gene Ontology:
Molecular function: alpha-galactosidase activity; catalytic activity; protein binding; protein homodimerization activity; signaling receptor binding; hydrolase activity; hydrolase activity, hydrolyzing O-glycosyl compounds
Biological process: glycosphingolipid catabolic process; oligosaccharide metabolic process; glycoside catabolic process; glycosylceramide catabolic process; negative regulation of nitric oxide biosynthetic process; negative regulation of nitric-oxide synthase activity; carbohydrate metabolic process
Cellular component: cytoplasm; extracellular exosome; extracellular region; Golgi apparatus; lysosome; azurophil granule lumen; lysosomal lumen
Gene-disease validity (ClinGen):
ClinGen rates the evidence that GLA causes each of these diseases.
Fabry disease (X-linked): Definitive. Fabry disease (FD) is a progressive, inherited, multisystemic lysosomal storage disease characterized by specific neurological, cutaneous, renal, cardiovascular, cochleo-vestibular and cerebrovascular manifestations.
Homologues: Orthologues: chimpanzee GLA (99% identical), macaque GLA (98% identical), dog GLA (81% identical), pig GLA (81% identical), guinea pig GLA (81% identical), mouse Gla (76% identical), rat Gla (76% identical), zebrafish gla (62% identical), tropical clawed frog gla (62% identical), Drosophila melanogaster CG5731 (44% identical), Drosophila melanogaster CG7997 (43% identical), Caenorhabditis elegans gana-1 (41% identical). Paralogues in human: NAGA (46% identical).
Diseases named in the same sentence as GLA in open-access papers:
GLA is named in the same sentence as 178 diseases in open-access papers, as found by Europe PMC text mining. Sharing a sentence is not in itself a finding about the gene and the disease. The quoted sentences say what the papers report.
Fabry disease (591 papers, 2007 to 2026). "Anderson-Fabry disease (AFD) is an X-linked lysosomal storage disorder caused by mutations in the GLA gene, leading to deficient α-galactosidase A activity." (PMID 41645402, 2026). "Fabry disease (FD) is a rare lysosomal storage disorder caused by mutations in the GLA gene, resulting in globotriaosylceramide accumulation." (PMID 41526641, 2026). "Fabry nephropathy is a major cause of kidney failure in Fabry disease, caused by pathogenic GLA variants that reduce α-galactosidase A activity and lead to globotriaosylceramide (Gb3) accumulation." (PMID 42212514, 2026). "Fabry disease (FD) is a rare X-linked lysosomal storage disorder caused by variants in the alpha-galactosidase A gene (GLA)." (PMID 41545379, 2026). "In particular, excessive cardiac damage is the most frequent cause of mortality in Fabry disease (FD), a genetic condition caused by deficient α-galactosidase A (GLA) activity, leading to globotriaosylceramide (Gb3) accumulation." (PMID 42039572, 2026). "The identification of these new mutations in patients with symptoms attributable to Fabry disease increases the molecular knowledge of the GLA gene and provides important support to the clinician, for a more accurate and timely diagnosis of the pathology." (PMID 39859188, 2025). "Fabry disease (FD) is a rare, progressive, X-linked genetic disorder caused by pathogenic variants of the GLA gene, leading to a deficiency in the lysosomal α-galactosidase-A enzyme." (PMID 40524234, 2025). "These processes included monosaccharide metabolic processes, which are consistent with GLA enzyme deficiency in Fabry disease." (PMID 40673439, 2025). "Fabry disease (FD) is a rare genetic disorder caused by mutations in the GLA gene, affecting multiple organs." (PMID 40520931, 2025). "Regarding the lysosomal enzymes, two patients had heterozygous variants in GALC (Krabbe disease) and GLA (Fabry disease)." (PMID 40542290, 2025). "Fabry Disease (FD) is an X-linked lysosomal storage disorder caused by mutations in the GLA gene (Xq22.1), encoding α-galactosidase A (α-Gal A)." (PMID 40784937, 2025). "De novo somatic mosaicism was suggested to be a disease modifier in a 34-year-old male patient with late-onset Fabry disease with a classical GLA mutation and mild organ involvement." (PMID 41150803, 2025). "Migalastat is an alpha-galactosidase A chaperone that is used for Fabry disease in patients with an amenable galactosidase alpha gene variant." (PMID 40149863, 2025). "Fabry disease is a rare X-linked disease caused by pathogenic mutations in the galactosidase alpha (GLA) gene." (PMID 40905915, 2025). "Fabry disease (FD) results from pathogenic galactosidase A (GLA) variants, leading to a deficiency in lysosomal α-galactosidase A (α-Gal A) and accumulation of the sphingolipid globotriaosylceramide (Gb3)." (PMID 41463452, 2025). "The identification of novel variants in individuals exhibiting symptoms indicative of Fabry disease, expands the molecular comprehension of the GLA gene, providing invaluable insights to physicians in the diagnosis of the disease." (PMID 39859185, 2025). "Although Fabry disease is X‐linked, GLA gene variants in females can exhibit a wide range of symptoms, challenging the traditional view of Fabry as an X‐linked recessive disease." (PMID 39822326, 2025). "Fabry disease (FD) is an X-linked lysosomal storage disorder resulting from a mutation in the GLA gene, which leads to deficiency or reduced activity of the enzyme α galactosidase A (α-GalA)." (PMID 40149601, 2025). "Fabry disease (FD) is a rare, X-linked lysosomal storage disease caused by variants in the α-galactosidase A gene (GLA) that result in deficient α-galactosidase A enzyme (α-Gal A) activity." (PMID 40725823, 2025). "A similar challenge exists for the GLA gene, implicated in Fabry disease, where a minority of pathogenic variants are deep intronic and population-specific." (PMID 41300778, 2025).
Fabry disease (continued). "Fabry disease is a rare X-linked lysosomal storage disorder caused by mutations in the GLA gene which encodes the α-GalA enzyme." (PMID 39931243, 2025). "Classic Fabry disease is caused by severe alpha-galactosidase A (GLA) deficiency, has a multi-organ phenotype, and the enzyme activity is abolished or close to zero." (PMID 38937656, 2025). "It should be noted that a marked reduction in GLA activitydue to mutations in the GLA gene leads to a rare lysosomalstorage disorder, Fabry disease." (PMID 41164274, 2025). "Fabry disease is an X‐linked lysosomal disorder of the GLA gene on chromosome Xp22.1, encoding alpha‐galactosidase (alpha‐Gal A)." (PMID 39822326, 2025). "Of the 14 initially enrolled patients, 8 (57%) had to be excluded from the final analysis due to atypical GLA gene mutations, which led to very atypical or even asymptomatic presentations of Fabry disease." (PMID 40874831, 2025). "Fabry disease is a rare X-linked lysosomal storage disorder caused by mutations in the GLA gene, resulting in deficient alpha-galactosidase A activity." (PMID 41550309, 2025). "Fabry disease (FD) is a rare X-linked lysosomal storage disorder caused by mutations in the GLA gene, resulting in a deficient activity of the enzyme α-galactosidase A (α-Gal A)." (PMID 40806187, 2025). "Dysregulated methylation of the GLA gene was also shown to be associated with impairment of autophagy in Fabry disease." (PMID 41150803, 2025). "For example, Fabry disease, caused by hemizygous- or heterozygous-pathogenic variants in GLA encoding human-galactocersbrosidase-α (hGLA), is a rare, single protein-deficiency disease." (PMID 41171941, 2025). "Fabry disease (FD) is an X-linked metabolic disorder caused by a genetic defect in the GLA gene located in the Xq22 region, which encodes the lysosomal enzyme α-galactosidase A (α-Gal A)." (PMID 40898253, 2025). "Later, in 1985, the genetic background of Fabry disease was confirmed by Robert J. Desnick’s group by discovering a mutation in the GLA gene." (PMID 41465551, 2025). "Fabry disease (FD) (OMIM #301500) is a rare X-linked disorder caused by mutations in the galactosidase alpha (GLA) gene affecting approximately 1 in 40,000 males and 1 in 20,000 females." (PMID 41204227, 2025). "Fabry disease (FD; OMIM #301500), also known as Anderson-Fabry disease, is a rare X-linked lysosomal storage disorder caused by mutations in the GLA gene encoding α-galactosidase A (α-GalA), which is located on chromosome Xq22.1." (PMID 41573578, 2025). "Another female patient with GBA1: p.R434P carried a heterozygous variant in GLA related to X-linked Fabry disease (c.937G > T chrX-101398432 C > A p.Asp313Tyr NM_000169.3)." (PMID 40542290, 2025). "Fabry disease (FD) is a rare X-linked lysosomal storage disorder caused by an inherited deficiency of lysosomal α-galactosidase A, resulting from mutations in the GLA gene." (PMID 41473230, 2025). "Fabry disease (FD) is an X-linked lysosomal disorder caused by GLA mutations, typically associated with glycosphingolipid accumulation and a wide phenotypic spectrum." (PMID 41516147, 2025). "Fabry disease (FD) is a rare X-linked lysosomal storage disorder caused by pathogenic variants in the GLA gene located at Xq22.1." (PMID 41584929, 2025). "Fabry disease is a rare, chronic, progressive, X-linked lysosomal disorder caused by variants in the galactosidase alpha (GLA) gene leading to a deficiency in α-galactosidase A enzyme activity." (PMID 40520913, 2025). "Fabry disease is caused by a deficiency in the GLA gene that codes for α-galactosidase A, a lysosomal hydrolase." (PMID 40650054, 2025). "In humans, mutations in the gene for α-galactosidase A (GLA) lead to an X-linked, multisystemic, highly heterogenic, possibly life-threatening lysosomal storage disorder known as Fabry disease (FD)." (PMID 40005114, 2025).
Fabry disease (continued). "The analysis of variants in the GLA gene is an essential step in the correct diagnosis of Fabry disease in individuals with a clinical suspicion of the condition." (PMID 39859185, 2025). "Fabry disease (FD) is a rare X-linked lysosomal storage disease caused by defective variants in the GLA gene that encodes the alpha-galactosidase A (α-Gal A) enzyme." (PMID 40276560, 2025). "Fabry disease (FD) is an X-linked, multisystemic, progressive lysosomal disorder caused by GLA variants resulting in alpha-galactosidase A deficiency, and subsequent lysosomal accumulations of glycosphingolipids and cellular dysfunction in many organs." (PMID 40722192, 2025). "To date, more than 1000 mutations in the GLA gene responsible for Fabry disease have been described, including missense, nonsense, and small and large deletions/insertions." (PMID 39859188, 2025). "Fabry disease (FD) is an X-linked lysosomal storage disorder caused by mutations in the α-galactosidase A (GLA) gene, leading to an increased risk for white matter lesion (WML), stroke and cerebral microbleeds." (PMID 41402951, 2025). "Fabry disease is a rare, multisystem, progressive X‐linked lysosomal disorder caused by the functional deficiency of α‐galactosidase A enzyme due to GLA gene variants." (PMID 39031114, 2025). "Fabry disease (FD) is a rare, progressive disorder caused by pathogenic variants of the GLA gene resulting in the accumulation of toxic metabolites." (PMID 40524234, 2025). "Fabry disease (OMIM 301500), also known as Anderson–Fabry disease, is an X-linked lysosomal storage disorder caused by mutations in the α-galactosidase A (GLA) gene." (PMID 41463072, 2025). "Fabry disease (FD), a lysosomal storage disorder, is a rare monogenic single protein deficiency disease caused by pathogenic variants in the GLA gene." (PMID 41171875, 2025). "In Fabry disease, GLA gene mutations cause impaired α-galactosidase A activity leading to the ineffective degradation of lipid substrates in cells, resulting in massive accumulation." (PMID 38474401, 2024). "Subsequent genetic testing revealed a pathogenic variant in the GLA gene, confirming Fabry disease and highlighting the critical need for genetic analysis in cases of unexplained renal pathology." (PMID 39092329, 2024). "Fabry disease (FD) is a lysosomal storage disorder caused by deficiency of the enzyme α-Gal due to mutations in the GLA gene located on the X chromosome." (PMID 38820517, 2024). "Fabry disease (FD) is an X-linked recessive disorder caused by GLA mutations that result in deficient lysosomal α-galactosidase A (GLA) activity." (PMID 38903807, 2024). "Fabry disease is caused by a deficiency or dysfunction of α-Gal A level due to mutations in the GLA gene and presents a wide range of symptoms." (PMID 39119442, 2024). "Fabry disease (FD) is an X-linked disorder resulting in a deficiency of α-galactosidase A (GLA) activity." (PMID 38903807, 2024). "Fabry disease (FD) is an inherited X-linked lysosomal storage disorder due to the impaired activity of the α-galactosidase A (GLA) enzyme." (PMID 38327490, 2024). "Fabry disease (FD) is an X-linked lysosomal storage disorder resulting from pathogenic mutations in the galactosidase alpha (GLA) gene." (PMID 39684857, 2024). "Despite the initial clinical diagnosis of primary HCM, genetic testing for Fabry’s disease was performed, leading to the identification of a disease-causing variant in the GLA gene, thereby supporting the diagnosis of Fabry’s disease." (PMID 39161721, 2024). "In the second case, a female patient suspected of having Fabry disease, an X-linked disorder associated with the GLA gene based on clinical and biochemical findings was tested for skewed X-inactivation using our method." (PMID 38627676, 2024). "In this paper, we report the interesting case of a young woman with an exonic mutation in the GLA gene, c.718_719delAA, responsible for the classic, severe phenotype of Fabry disease." (PMID 38791200, 2024).
Fabry disease (continued). "Genetic testing identified a pathogenic variant in the GLA gene (c.644A>G) (p.Asn215Ser), confirming the diagnosis of Fabry’s disease, with an additional variant of uncertain significance in FHL1." (PMID 39161721, 2024). "Fabry disease (FD) is caused by mutations in the galactosidase alpha (GLA) gene which lead to the accumulation of globotriaosylceramide (Gb-3)." (PMID 38613094, 2024). "Fabry disease (FD) is an X-linked genetic lysosomal storage disease caused by mutations in the GLA gene coding for a functional alpha-galactosidase A enzyme, which is important in the metabolism of sphingolipids." (PMID 39685527, 2024). "In a previous study, we identified four GLA mutations from four independent Fabry disease families, GLA c.119C>A (p.P40H), c.280T>C (p.C94R), c.680G>C (R227P), and the splicing mutation c.801+1G>A." (PMID 38474401, 2024). "Fabry disease (FD) is a rare X‐linked lysosomal storage disorder caused by variants in GLA gene leading to deficient α‐galactosidase A enzyme activity." (PMID 38895855, 2024). "Fabry disease is a progressive X-linked inherited lysosomal storage disorder caused by mutations in the GLA gene leading to deficient α-galactosidase (α-Gal) A activity, glycosphingolipid accumulation, and potentially life-threatening complications." (PMID 38308295, 2024). "Fabry disease is an X-linked lysosomal storage disorder caused by mutations in the GLA gene encoding α-Gal A. Glycosphingolipids, particularly Gb3 and Lyso-Gb3, accumulate in the context of α-Gal A deficiency." (PMID 38392324, 2024). "More than 1100 mutations of the GLA gene that are associated with Fabry disease have been described in the literature to date." (PMID 39685527, 2024). "Fabry disease is an X-linked lysosomal storage disorder caused by mutations in the alpha galactosidase A gene (GLA)." (PMID 39110386, 2024). "Fabry disease (FD) is an X-linked disorder of glycosphingolipid metabolism caused by mutations in the GLA gene encoding alpha-galactosidase A (α-Gal)." (PMID 38820517, 2024). "Fabry disease (FD) is a rare X-linked lysosomal storage disorder marked by alpha-galactosidase-A (α-Gal A) deficiency, caused by pathogenic mutations in the GLA gene, resulting in the accumulation of glycosphingolipids within lysosomes." (PMID 39390597, 2024). "Fabry Disease (FD) is a multiorgan X-linked lysosomal storage disorder caused by mutation in the GLA gene (Xq22.1), encoding for the α-galactosidase A (α-GalA) enzyme." (PMID 38771548, 2024). "Fabry Disease (FD) is one of the most prevalent lysosomal storage disorders, resulting from mutations in the GLA gene located on the X chromosome." (PMID 38667269, 2024). "In the range of cells affected by the mutation in the GLA gene and contributing to the Fabry disease phenotype, endothelial cells also represent an important part." (PMID 39449071, 2024). "Fabry disease, caused by mutations in the α‐galactosidase A (GLA) gene, leads to enzyme deficiency and globotriaosylceramide accumulation in various cell types." (PMID 39156766, 2024). "To reveal the molecular mechanism underlying the predisposition to Fabry disease caused by GLA mutations, we analyzed the effects of these four GLA mutations on the protein structure of α-galactosidase A using bioinformatics methods." (PMID 38474401, 2024). "Fabry disease, an X-linked lysosomal storage disorder caused by galactosidase α (GLA) gene mutations, exhibits diverse clinical manifestations, and poses significant diagnostic challenges." (PMID 39466827, 2024). "Considering the association between the GLA gene and Fabry disease, plasma GLA levels and globotriaosylsphingosine (Lyso-GL-3) levels were measured." (PMID 39650153, 2024).